CARM1 (coactivator associated arginine methyltransferase 1)
Diseases named in the same sentence as CARM1 in open-access papers (continued):
Sharing a sentence is not in itself a finding about the gene and the disease.
ovarian carcinoma (continued). "Together, these observations support that CAY10566, a SCD1 inhibitor, is effective in suppressing ovarian cancer with high expression if CARM1 in vivo, and this effect is correlated with the inhibition of cell proliferation and the induction of apoptosis." (PMID 37377614, 2023). "In summary, our data show that CARM1 reprograms fatty acid metabolism and targeting SCD1 through pharmacological inhibition can serve as a potent therapeutic approach for CARM1-expressing ovarian cancers." (PMID 37377614, 2023). "Here we report that CARM1 promotes monounsaturated fatty acid synthesis and fatty acid reprogramming represents a metabolic vulnerability for CARM1-expressing ovarian cancer." (PMID 37377614, 2023). "Among all cancers, ovarian cancers present the highest alteration frequency of CARM1 (> 8%) with “amplification” as the primary type." (PMID 35033016, 2022). "Inhibition of the IRE1α/XBP1s pathway was effective against ovarian cancer in a CARM1-dependent manner both in vitro and in vivo in orthotopic and patient-derived xenograft models." (PMID 34493732, 2021). "Here, we report that CARM1-expressing ovarian cancer cells are selectively sensitive to inhibition of the IRE1α/XBP1s pathway." (PMID 34493732, 2021). "Here we show that pharmacological targeting of the IRE1α/XBP1s pathway selectively suppresses CARM1-expressing ovarian cancer, which further synergizes with immune checkpoint blockade." (PMID 34493732, 2021). "Here the authors show that CARM1, an arginine methyltransferase, controls the IRE1α/XBP1 pathway of the UPR and the inhibition of this pathway can inhibit growth in CARM1 expressing ovarian cancers." (PMID 34493732, 2021). "For example, EZH2 inhibitor inhibits the growth of ovarian cancer cells which are positive for arginine methyltransferase PRMT4/CARM1, which itself is upregulated in ovarian cancer." (PMID 31426393, 2019). "The knockdown of CARM1 as well as NAC1 using siRNA suppressed cell growth in the ovarian carcinoma cell lines A2780 and MDAH2774." (PMID 29983869, 2018). "Here, the authors show that EZH2 inhibition suppresses growth in CARM1-expressing epithelial ovarian cancer, and examine the mechanism of how CARM1 promotes EZH2-mediated tumor suppressor gene silencing." (PMID 29434212, 2018). "In accordance with the patient findings, knockdown of NAC1 and CARM1 in ovarian cancer cell lines resulted in cell growth inhibition." (PMID 29983869, 2018). "In contrast to our prediction that CARM1 would be highly expressed in steroid receptor-rich tumors, CARM1 was only overexpressed in a small fraction of these tumors (27% of breast tumors, 6% of prostate cancers, and 17% of ovarian cancers)." (PMID 20462455, 2010). "They found that inhibiting the fatty acid desaturase SCD1 could serve as an effective treatment method for ovarian cancer with high CARM1 expression." (PMID 39964832, 2025). "A reasonable explanation is that XBP1s may have promoted PD1 expression in a CARM1-expressing ovarian cancer model and thus increased the efficacy of anti-PD1 therapy." (PMID 38297380, 2024). "Indeed, SCD1 inhibition demonstrated efficacy against ovarian cancer in both orthotopic xenograft and syngeneic mouse models in a CARM1-dependent manner." (PMID 37377614, 2023). "Consequently, inhibition of SCD1 suppresses the growth of ovarian cancer cells in a CARM1 status–dependent manner, which was rescued by the addition of monounsaturated fatty acids." (PMID 37377614, 2023). "CARM1 is often overexpressed in human cancers including in ovarian cancer." (PMID 34493732, 2021). "In addition, IRE1α inhibitor B-I09 synergizes with immune checkpoint blockade anti-PD1 antibody in an immunocompetent CARM1-expressing ovarian cancer model." (PMID 34493732, 2021).
ovarian carcinoma (continued). "Biochemically, as a cofactor for several transcription factors and nuclear hormone receptors, the histone methyltransferase of CARM1 belongs to a family of arginine methyltransferases, and is involved in the tumorigenesis of various cancers, such as ovarian cancer." (PMID 31799198, 2019). "In agreement with these previous studies, we showed that CARM1 is overexpressed in human ovarian cancers (30/84, 35.7%), with significant correlation of high NAC1 expression levels, and elevated levels of NAC1 and CARM1 correlate with poor prognosis after adjuvant chemotherapy." (PMID 29983869, 2018). "Based on the concept of ‘oncogene addiction’, CARM1 may represent a novel therapeutic target in ovarian cancer." (PMID 29983869, 2018). "Collectively, our results demonstrate that high expression levels of NAC1 and its novel binding partner CARM1 may serve as an informative prognostic biomarker for predicting resistance to chemotherapy for ovarian cancer." (PMID 29983869, 2018). "Here, we report that EZH2 inhibition is effective in CARM1-expressing epithelial ovarian cancer." (PMID 29434212, 2018). "Furthermore, the study found that NAC1 is not only a transcriptional repressor but may also act as a transcriptional activator, cooperating with its interacting partner CARM1 to exert carcinogenic potential in ovarian cancer cells." (PMID 39964832, 2025). "This raises the possibility that diets or interventions that lowers lipid to increases saturated FAs may further improve the antitumor effects of SCD1 inhibition–based therapeutic approaches for several cancer types with frequent CARM1 overexpression and amplification including ovarian cancer." (PMID 37377614, 2023). "Notably, CARM1 is most amplified in ovarian cancer based on TCGA database." (PMID 37377614, 2023). "In addition, the CARM1 protein expression level of 21–40 years old group in ovarian cancer patients is up-regulated compared with other age groups, which may be a potential feature of this group." (PMID 35033016, 2022). "Thus, high expression levels of NAC1 and CARM1 may serve as an informative prognostic biomarker for predicting resistance to chemotherapy for ovarian cancer." (PMID 29983869, 2018). "In a CARM1-dependent way, EZH2 inhibitors can increase MAD2L2 and make HR-proficient ovarian cancer more sensitive to PARPi." (PMID 40612876, 2025). "Consistently, across a range of ovarian cancer cell lines with established CARM1 expression status, IC50s of CAY10566 were significantly lower in CARM1-high versus CARM1-low expression cells." (PMID 37377614, 2023). "In the current study we show that CARM1 promotes de novo FAs and subsequent MUFA synthesis, and SCD1 inhibition represents a therapeutic strategy for CARM1-expressing ovarian cancer." (PMID 37377614, 2023). "Ovarian cancer patients expressing high levels of NAC1 and CARM1 exhibited poor prognosis after adjuvant chemotherapy." (PMID 29983869, 2018). "The significant correlation of CARM1 and NAC1 expression levels implies that NAC1 functions synergistically with at least CARM1 to promote tumorigenesis in ovarian cancers." (PMID 29983869, 2018). "In an attempt to determine the expression levels of CARM1 and NAC1 in clinical specimens, we performed immunohistochemistry (IHC) for CARM1 and NAC1 in 84 ovarian carcinoma tissues." (PMID 29983869, 2018). "Following further investigation, the team found that EZH2 inhibitors increased the expression of MAD2L2 and rendered HR‐proficient epithelial ovarian cancer (EOC) sensitive to poly (adenosine diphosphate‐ribose) polymerase (PARP) inhibitors, dependent on CARM1." (PMID 39964832, 2025). "Furthermore, ovarian cancer patients expressing high levels of NAC1 and CARM1 exhibited poor prognosis after adjuvant chemotherapy." (PMID 29983869, 2018). "The immunofluorescence experiment was next performed on BG-1 cells, an ER+ ovarian cancer cell line, to verify CARM1 isoform localization was not cell line or cancer-type specific." (PMID 26030442, 2015).
ovarian carcinoma (continued). "Besides, in HR-proficient ovarian cancer, EZH2 inhibition could promote sensitivity to PARP inhibitors via upregulation of MAD2L2 in a CARM1-dependent manner." (PMID 36793373, 2023). "Thus, CARM1 overexpression and/or amplification may serve as a predictive marker for further development of EZH2 inhibitor as a potential therapy in ovarian cancer." (PMID 29434212, 2018). "Thus, CARM1 may play a role in ovarian cancer progression in collaboration with NAC1, and high expression levels of NAC1 and CARM1 may serve as an informative prognostic biomarker for predicting resistance to chemotherapy for ovarian cancer." (PMID 29983869, 2018). "A related follow-up study showed that an EZH2 inhibitor sensitizes CARM1-high, but not CARM-low, HR-proficient epithelial ovarian cancer cells to PARP inhibitors." (PMID 37536629, 2023). "As for ovarian cancer, low CARM1 expression is related to poor PFS, while the relationship between CARM1 expression and OS, PPS prognosis are not detected." (PMID 35033016, 2022). "Even though we could not validate if NAC1 immnoprecipitated NCOA3 in several ovarian cancer cell lines due to the quality of anti-NCOA3 antibody which could not detect endogenous NCOA3 expression, it is highly possible that NAC1 formed protein complex with CARM1 and NCOA3." (PMID 29983869, 2018).
lung carcinoma (18 papers, 2010 to 2025). "Alternative splicing of coactivator‐associated arginine methyltransferase 1 (CARM1) by epithelial splicing regulatory protein 1 (ESRP1) resulted in lung cancer cells sensitize to chemotherapy." (PMID 37168687, 2023). "CARM1-KD promotes the proliferation of lung cancer cells, and the down-regulation of CARM1 significantly inhibits the proliferation of gastric cancer cells." (PMID 37477799, 2023). "It is reported that CARM1 acts as an oncogene in human cancers including ovarian, breast and lung cancers." (PMID 33593309, 2021). "LncRNA PVT1 may promote cell apoptosis through the miR-424-5p/PVT1/CARM1 signaling pathway, thereby enhancing the radiosensitivity of lung cancer cells." (PMID 37056929, 2023). "Specific targets, such as PRMT1, KDM6B, CARM1, BRD4, and EZH2, have been shown to be associated with malignant phenotypes of lung cancer, influencing cell proliferation and metastatic processes (regulation of epithelial–mesenchymal transition and cell invasion)." (PMID 36233212, 2022). "The combination of the CARM1 inhibitor EZM2302 and an anti-PD-1 antibody exerted promising synergistic effects on a preclinical model of lung cancer." (PMID 40016178, 2025).
multiple myeloma (16 papers, 2017 to 2025). "They noted high expression of CARM1 in patients with multiple myeloma, especially in those with stage III or relapsed/refractory MM, which is closely linked to poor prognosis." (PMID 39964832, 2025). "Drew identified the CARM1 inhibitor EZM2302 (GSK3359088) with potent in vitro activity in preclinical models of aggressive myeloma, and treatment with EZM2302 in MM cell lines inhibited PABP1 and SMB methylation and cellular arrest." (PMID 39964832, 2025). "This includes specific resistance to the proteasome inhibitor bortezomib in multiple myeloma, which is driven by an N6-methyladenosine (m6A)-mediated upregulation of lncRNA H19, functioning as a sponge to regulate the miR-184/CARM1 axis." (PMID 41379397, 2025). "This study is also the first to our knowledge in which a potential role for CARM1 as a driver in multiple myeloma has been reported." (PMID 29269946, 2017). "EZM2302 is a tool compound that can be used to further explore the biological role of CARM1 and understand the role of this enzyme in multiple myeloma and other oncology indications." (PMID 29269946, 2017). "Studies have reported that the use of selective inhibitors of CARM1 inhibits the proliferation of multiple myeloma cell lines and that affected cells are blocked in the G1 phase, which is consistent with our findings using shRNA to knock down CARM1 expression in MM cells." (PMID 37477799, 2023). "H3R17me2 is associated with transcriptional activation based on the recruitment of polymerase-associated factor 1 complex to initiate transcription in humans, supported by the antiproliferative effects of a specific CARM1 inhibitor on multiple myeloma cell lines." (PMID 35051657, 2022). "EZM2302 demonstrates in vitro anti-proliferative activity consistent with specific methyl mark inhibition; displays dose-dependent inhibition of CARM1 substrate methylation in vivo; and induces growth inhibition of human multiple myeloma tumor xenografts in mice after oral dosing." (PMID 29269946, 2017). "Importantly, this is the first report to our knowledge that demonstrates a potential role for a CARM1 inhibitor in multiple myeloma." (PMID 29269946, 2017). "For example, the CARM1-specific inhibitors TP-064 and EZM2302 have demonstrated their effectiveness as promising therapeutic interventions for multiple myeloma." (PMID 40016178, 2025). "To exclude the possibility that the decrease in SEs is TP-064-specific, we employed another CARM1-specific inhibitor, EZM2302, which is orally bioavailable, and has been shown to elicit in vivo anti-cancer effects in multiple myeloma." (PMID 34865122, 2021). "In comparison to SKI-73 (6a), the CARM1 inhibitors EZM2302 and TP-064 demonstrated anti-proliferation effects on hematopoietic cancer cells, in particular multiple myeloma." (PMID 31657716, 2019). "This work demonstrates anti-proliferative effects of CARM1 inhibition by EZM2302 treatment in hematopoietic cancer cell lines, which were most frequently observed in multiple myeloma cell lines." (PMID 29269946, 2017). "We believe this is a novel finding, as no previous work to our knowledge suggests a role for CARM1 in multiple myeloma pathogenesis." (PMID 29269946, 2017).
multiple myeloma (continued). "Similar inhibition of methylation of CARM1 substrates was observed after 21-day treatment of a second multiple myeloma xenograft mouse model, NCI-H929, but in this case no significant anti-tumor effects were observed (data not shown)." (PMID 29269946, 2017).
prostate carcinoma (16 papers, 2010 to 2025). A carcinoma that arises from epithelial cells of the prostate gland. "It has been found that overexpression of CARM1 is associated with the development of prostate cancer (PCa) and its progression to androgen-independent PCa." (PMID 37228649, 2023). "Correspondingly, overexpression of CARM1 has been associated with the development of prostate cancer (PCa) and its progression to androgen-independent PCa." (PMID 20462455, 2010). "The findings showed that CARM1 was generally underexpressed in prostate cancer cells excluding PC3 and DU145, AR-deficient cells." (PMID 20462455, 2010). "Treatment with C3 results in diminished AR binding to target genes and reduced recruitment of AR and β‐catenin co‐factors, such as CARM1, thus triggering prostate cancer cell death." (PMID 39964832, 2025). "Grypari's research found that PRMT1 and CARM1 are upregulated in the early stages of prostate cancer progression, with CARM1 further upregulated after treatment." (PMID 39964832, 2025). "CARM1 is essential in the oncogenic growth of prostate cancer, and overexpression of CARM1 in PCa correlates with androgen signalling, cell cycle, and EMT regulators." (PMID 37528657, 2023). "PRMT4 (also known as CARM1) is overexpressed in several solid tumors, including breast, prostate cancer, and hepatocellular carcinoma." (PMID 33076518, 2020). "PRMTs, like the coactivator-associated arginine methyl-transferase (CARM1) and PRMT5, have been described to play an important role in cancer as their expression increases in breast and prostate cancers, for CARM1, and lymphoma, for PRMT5." (PMID 23016851, 2013). "Previously, CARM1 was shown to be overexpressed in both androgen-sensitive tumors and androgen-independent tumors with increased expression in castration-resistant prostate cancers." (PMID 20462455, 2010). "CARM1 has been reported to be overexpressed in androgen-resistant prostate cancers when compared to androgen-dependent cancers." (PMID 20462455, 2010). "In this study, however, the CARM1 expression was low in most prostate cancers, including both androgen-sensitive and androgen-resistant tumors." (PMID 20462455, 2010). "First, quantitative RT-PCR and Western blot analyses were performed to confirm the CARM1 expression level in various prostate cancers." (PMID 20462455, 2010). "CARM1 directly interacts with β-Catenin, and because there is crosstalk between AR and β-Catenin in castration-resistant prostate cancer, these cancers may be vulnerable to CARM1i." (PMID 37536629, 2023). "The ability of CARM1 to coactivate NRs may be clinically important for NR-driven cancers like BC and prostate cancer." (PMID 37536629, 2023). "At the same time, malignant progression of prostate cancer might be achieved by androgen-independent activity of CARM1." (PMID 20462455, 2010). "CARM1's overexpression during the development of prostate cancer continues to be debated." (PMID 20462455, 2010). "The anti-proliferative effect of EZM2302 treatment was assessed in a panel of solid tumor cell lines representing indications in which CARM1 has been hypothesized in the literature to play an oncogenic role, including breast, colorectal, and prostate carcinoma." (PMID 29269946, 2017). "The team successfully identified a novel dual‐target inhibitor of CARM1/HDAC2, potentially playing a crucial role in prostate cancer therapy." (PMID 39964832, 2025). "In human breast and prostate cancer cells, CARM1/PRMT4 knockdown resulted in the inhibition of cell proliferation and cell cycle progression and in the enhancement of cell apoptosis." (PMID 23202904, 2012). "The results of this study showed that CARM1 overexpression was not generally observed using a prostate cancer tissue microarray." (PMID 20462455, 2010). "In contrast to previous reports, however, CARM1 expression was not altered during androgen-independent progression of prostate cancer as shown by the dot-plot analysis." (PMID 20462455, 2010).
prostate carcinoma (continued). "In contrast to previous reports, CARM1 was not overexpressed in the androgen sensitive and androgen-resistant prostate cancers." (PMID 20462455, 2010).